AIM2 (absent in melanoma 2)
Diseases named in the same sentence as AIM2 in open-access papers (continued):
Sharing a sentence is not in itself a finding about the gene and the disease.
Stroke (continued). "Together, these observations may suggest a role for the Aim2 inflammasome activation in TBI and stroke-associated neuroinflammation." (PMID 31771614, 2019). "Therefore, the activation of AIM2 might exacerbate stroke pathology by inducing excessive T cell death." (PMID 39600708, 2024). "Additionally, the role of the AIM2 inflammasome was examined in stroke-induced cognitive impairment in elderly mice, which demonstrated that AIM2 mRNA and protein, combined with caspase-1, IL-1β, and IL-18, were enhanced in the hippocampus and cortex after stroke." (PMID 37450925, 2023). "AIM2 inflammasome‐mediated pyroptosis may aggravate cognitive impairment after stroke." (PMID 37125240, 2023). "Moreover, knockout of AIM2 or inhibition of caspase-1 could improve cognitive function and partly reverse brain volume in the hippocampus compared to those in stroke mice." (PMID 37332874, 2023). "However, it is currently unclear whether pyroptosis occurs within brain cells following stroke and whether A151 treatment could influence AIM2 activation and pyroptosis in ischemic brain." (PMID 32239625, 2020). "In this study, we examined the expression patterns of the AIM2 inflammasome and other cytoplasmic PRRs, including NLRP1a, NLRP3, and NLRC4, in mice after stroke and found that AIM2 and NLRP3 were activated 7 days after cerebral ischemia." (PMID 39854137, 2025). "Our findings indicated that 3‐HKA enhances vascular remodeling via regulation of the astrocyte A1/A2 transition by impeding AIM2 inflammasome activation, suggesting a previously overlooked mechanism by which 3‐HKA promotes recovery after stroke." (PMID 39854137, 2025). "First, given the complexity of stroke pathogenesis, the relevance of crosstalk between the NRF/ARE pathway and the NF-κB/AIM2 pathway during PSCI is still unclear." (PMID 40351418, 2025). "Specifically, 14 days after stroke, damage to the BBB in the 3‐HKA‐treated group was greater than that in the vehicle‐treated group, and overexpression of AIM2 offset this protective effect." (PMID 39854137, 2025). "At 14 days after stroke, the number of newly formed microvessels was increased in the 3‐HKA‐treated group, but this increase was suppressed by AIM2 overexpression." (PMID 39854137, 2025). "AIM2 knockout and capase‐1 inhibitor Ac‐YVAD‐CMK treatment significantly improved cognitive function in stroke mice." (PMID 37125240, 2023). "Photobiomodulation (PBM) with 630 nm LED array affixed to the exposed skull of stroke mice model could significantly attenuate the progression of cognitive impairment in the chronic poststroke phase via regulating AIM2 inflammasome activation and AIM2 inflammasome-mediated pyroptosis." (PMID 37332874, 2023). "We detected the expression of three inflammasomes, AIM2, NLRC4, and Caspase-1 using immunofluorescence and found that the expression of the three inflammasomes was significantly decreased in stroke rats after THSWD administration." (PMID 36034843, 2022). "By comparison, it was found that the expression levels of AIM2, NLRC4, and Caspase-1 were significantly inhibited in the I/R + THSWD group after the gavage of THSWD to stroke rats." (PMID 36034843, 2022). "Next, we investigated the influence of stroke and EPO-administration on the activation of the inflammasomes NLRP3, NLRC4 and AIM2, and their downstreaming cascade." (PMID 34628598, 2022). "We observed DNA damage by gavage of THSWD in stroke rats and assessed the effect of THSWD on AIM2 and NLRC4 inflammasomes vesicles in rat brains after stroke." (PMID 36034843, 2022). "3‐HKA treatment resulted in a significant decrease in the mRNA level of AIM2 following stroke but had no obvious effect on NLRP3." (PMID 39854137, 2025). "Collectively, these results confirmed that 3‐HKA inhibited AIM2 inflammasome activation, promoting A2‐like polarization of astrocytes and resulting in increased astrocyte‐derived VEGF, which facilitated vascular remodeling after stroke." (PMID 39854137, 2025).
Stroke (continued). "Therefore, investigation the prognostic value of markers in the NETs/AIM2 inflammasome axis, such as MPO-DNA, PAD4, HMGB1, C1q, AIM2, ASC, Caspase-1, IL-1β, IL-6 and IL-8, in LAA stroke patients is a meaningful endeavor." (PMID 39737165, 2024). "Whereas NLRP3 and NOD2 deficiency did not improve outcome after experimental stroke, ASC-KO, AIM2-KO and NLRC4-KO mice had reduced infarct volumes." (PMID 37212886, 2023). "AIM2 is an inflammasome that is highly expressed in neurons after stroke and, unlike the NLRP3 inflammasome, is only activated by cytoplasmic dsDNA." (PMID 37165005, 2023). "A study found that AIM2 inflammasomes contributed to ASC to acute brain injury independent of NLRP3 after stroke." (PMID 35401398, 2022). "To determine which NLR sensor molecules were present in the clot of patients with stroke, we immunoblotted samples for NOD-like receptor protein-1 (NLRP1) and Absent in Melanoma-2 (AIM2); two receptors that form protein-protein interactions with caspase-1 and ASC to form an inflammasome complex." (PMID 33569001, 2020). "Vice versa, expression of NLRP3, but not those of NLRC4 and AIM2, was markedly increased in response to recurrent stroke evoked in the contralateral cortex, probably due to the antecedent ischemic stroke as a priming step for NLRP3 inflammasome activation." (PMID 32635451, 2020). "E2 administration prevented the post-stroke increase of Aim2 mRNA, wherein P failed to induce a significant reduction of the Aim2 transcript levels." (PMID 32645874, 2020). "In conclusion, the post-ischemic elevation of AIM2 and NLRC4 and their down-regulation by E2 and P may shed more light on the anti-inflammatory effects of both gonadal hormones after stroke." (PMID 32645874, 2020). "Finally, an expression analysis in the peri‐infarct zone of transient MCAO rats revealed elevated levels of the inflammasome components NLRP1, NLRP3, AIM2, NLRC4, and ASC, consistent with the potential activation of multiple inflammasomes in stroke." (PMID 31015277, 2019). "Cell-free DNA (cf-DNA), mainly originating from NETosis, was revealed that could activate absent in melanoma 2 (AIM2) inflammasome, contributing to the high recurrence rate after stroke." (PMID 39979243, 2025). "Although NLRP3 plays a significant role in post-stroke inflammation, there may be some residual protection even in the absence of NLRP3 due to compensatory pathways such as IL- 10/Jak-Stat stabilization and other inflammasomes like AIM2 and NLRC4." (PMID 40272769, 2025). "Pharmacological inhibition of NET formation with GSK484, a selective protein-arginine deiminase type 4 antagonist, suppressed NET production, reduced absent in melanoma 2 (AIM2) inflammasome expression, and improved neurological outcomes in mice following stroke." (PMID 40479571, 2025). "Moreover, caspase-1 activation was completely blunted in ASC-deficient or AIM2-deficient, but not in cGAS-deficient, NLRP1-deficient or NLRP3-deficient, BMDMs in response to stimulation with serum from stroke mice or stimulation with DNA." (PMID 39112714, 2024). "Our results demonstrated that, compared with those in the sham group, the mRNA levels of AIM2 and NLRP3, but not those of NLRP1a and NLRC4, were significantly elevated following stroke." (PMID 39854137, 2025). "It was shown that in early stroke NLRP1, NLRC4 or AIM2 did not have significant effects, while NLRP3 was predominantly expressed in ischemic neurons, and its inhibition improved neurologic outcome with a reduction in infarct size." (PMID 34112082, 2021).
breast carcinoma (32 papers, 2011 to 2025). "Both pyroptosis-related inflammasomes including NLRP1, NLRP3, NLRC4, AIM2, and the following inflammatory cytokines IL-1β and IL-18 are associated with the immune system in breast cancer." (PMID 36119049, 2022). "Those all indicated a potent antitumor activity of AIM2 and its association with immunity in breast cancer." (PMID 36119049, 2022). "Research has illuminated that the expression of AIM2 can suppress the proliferation and tumorigenicity of human breast cancer cells through the negative regulation of the TNF-α/NF-κB anti-apoptotic pathway." (PMID 40386782, 2025). "In vitro studies indicated the role of AIM2 as tumor suppressor and its capacity to inhibit breast cancer cell growth and proliferation via pyroptosis cell death." (PMID 39433537, 2024). "Further mechanistic investigations showed that dihydroartemisin activated the AIM2/caspase-3/DFNA5 pathway to induce the pyroptosis of breast cancer cells." (PMID 39202965, 2024). "While AIM2 level is reduced in breast cancer, prostate cancer, and hepatocellular carcinoma, it is overexpressed in nasopharyngeal carcinoma, cervical cancer, oral squamous cell carcinoma, and non-small cell lung cancer." (PMID 38186575, 2023). "Recently, Yaqiong Li found that DHA inhibited tumorigenesis by inducing AIM2/caspase-3/GSDME regulated pyroptosis in breast cancer cells." (PMID 36119049, 2022). "A previous study discovered that NLRP1, NLRP3, NLRC4, and AIM2 inflammasome complex proteins had pro- or antitumoral properties, especially in breast cancer." (PMID 36437954, 2022). "A recent study reported by Yaqiong Li indicated that breast cancer cells undergo pyroptosis via the AIM2/caspase-3/GSDME pathway active by DHA." (PMID 36119049, 2022). "In breast cancer treatment, Dihydroartemisinin induces pyroptosis in breast cancer cells by promoting the AIM2/caspase-3/DFNA5 (gasdermin E) axis." (PMID 36341437, 2022). "In particular, via controlling innate and adaptive immunity as well as tumor growth, NLRP1, NLRP3, NLRC4, and AIM2 have an effect on how breast cancer develops." (PMID 36119049, 2022). "In consistence with our study, AIM2 was demonstrated to inhibit proliferation and tumorigenicity in breast cancer, renal carcinoma, and prostate cancer." (PMID 33842454, 2021). "Macrophages can lead to immunosuppression of HER2+ breast cancers after antibody‐dependent cellular phagocytosis, in which AIM2 inflammasome plays a vital role." (PMID 34014039, 2021). "In a breast cancer model, AIM2 is reported to suppress cellular proliferation in vitro and mammary tumor growth within a mouse model." (PMID 33859277, 2021). "AIM2 expression suppressed the proliferation and tumorigenicity of human breast cancer cells, and AIM2 gene therapy inhibited mammary tumor growth in an orthotropic tumor model." (PMID 33162829, 2020). "AIM2 expression suppresses the proliferation and tumorigenicity of human breast cancer cells as well as mammary tumor growth in an orthotopic tumor model." (PMID 32397236, 2020). "In MCF7 breast cancer cell lines, AIM2 induction promotes apoptosis through the mitochondrial pathway and expression of pro-apoptotic proteins." (PMID 31205871, 2019). "AIM2 suppresses human breast cancer cell proliferation in vitro and mammary tumor growth in a mouse model." (PMID 31205871, 2019). "Overexpression of AIM2 has been shown to suppress proliferation of breast cancer cells and growth of xenografts." (PMID 28526809, 2017). "Therefore, further studies will be needed to clarify the role of the AIM2 inflammasome in breast cancer." (PMID 40002808, 2025). "Furthermore, AIM2 protein has exhibited potential in suppressing breast cancer cell proliferation and inducing cell apoptosis via inhibiting nuclear factor kappa-B activity." (PMID 38186575, 2023). "Besides, Dihydroartemisinin inducing pyroptosis via AIM2/caspase-3/DFNA5 axis was also reported in breast cancer." (PMID 35967354, 2022).
breast carcinoma (continued). "Taken together, these findings show that AIM2 exerts tumor suppression in breast cancer." (PMID 34014039, 2021). "Activation of AIM2 drives apoptosis and suppresses proliferation through antagonizing NF‐κB transcriptional activity and inhibiting antiapoptotic protein expression, thereby restraining mammary tumor growth in vivo." (PMID 34014039, 2021). "However, AIM2 activation in breast cancer cell line and the orthotopic mouse model of breast cancer exerts a protective action via suppressing NF-κB activation and inducing apoptosis among cancer cells." (PMID 33643304, 2020). "Hence, AIM2 suppression may promote breast cancer pathogenesis as mTOR-S6K1 signaling is increased in patients indicating its activity loss." (PMID 33643304, 2020). "Studies have shown a decrease in AIM2 expression in specific cancer types including CRC, breast cancer, HCC, HSCC, GC, and OS." (PMID 39744568, 2025). "According to reports, increased AIM2 inflammasome expression induced by interferon-γ (IFNγ) promotes apoptosis via the mitochondrial pathway and the regulation of proapoptotic proteins in MCF-7 breast cancer cells." (PMID 32397236, 2020). "Interestingly, the gene sets of ISs (AIM2, IFIH1 and TLR3), ISs and IFN-β (IFNB1), and all (ISs, IFNB1, IRF7 and TRAIL) showed strong correlations in ER-negative and lymph node positive or basal-like breast cancer patient survival." (PMID 27077807, 2016).
hepatocellular carcinoma (28 papers, 2016 to 2025). A malignant tumor that arises from hepatocytes. "Previous studies showed that AIM2 can prevent metastasis development of human renal carcinoma by promoting autophagy, whereas loss of AIM2 mediated by HBx can promote hepatocellular carcinoma metastasis." (PMID 36072791, 2022). "AIM2 was also reported to be down-regulated in hepatocellular carcinoma and loss of AIM2 expression contributed to hepatocarcinoma tumorigenesis and metastasis." (PMID 33291082, 2020). "Radiofrequency ablation on the proliferation of hepatoma cells is achieved through the induction of pyroptosis via the AIM2 inflammasome signaling pathway." (PMID 39917567, 2025). "Studies involving AIM2 silencing and overexpression in hepatocellular carcinoma cells further revealed that AIM2 exerts anti-tumor effects through inflammasome activity leading to pyroptosis." (PMID 37497237, 2023). "Compared with the terminally differentiated, normal, cancer-free tissues, the expression of AIM2 in hepatocellular carcinoma tissues was significantly reduced, and AIM2 expression was negatively correlated with tumor burden." (PMID 37497237, 2023). "AIM2 exhibited both growth inhibitory effects in colon, hepatoma, nasopharyngeal, and lung cancers, and proliferation-promoting effects in cutaneous squamous cell carcinomas (SCCs) and endometrial cancers." (PMID 35847844, 2022). "Similar to the finding in CRC, AIM2 expression in hepatocellular carcinoma (HCC) patient tissues was negatively correlated with HCC progression." (PMID 34697412, 2022). "Accordingly, the genetic deletion of AIM2 protected against tissue damage and cancer progression in the diethylnitrosamine‐induced hepatocellular carcinoma model." (PMID 34014039, 2021). "Lower levels of NLRP3, NLRP1, and AIM2 proteins were found in hepatocellular carcinoma (HCC), colorectal cancer (CRC), and gastric cancer (GC) compared to the adjacent normal tissue." (PMID 34298833, 2021). "Most studies describe an inflammasome-independent role of AIM2 in suppressing tumor growth, such as in colorectal cancer, breast cancer, cervical carcinoma, gastric cancer, hepatocellular carcinoma, osteosarcoma, and renal carcinoma." (PMID 41062723, 2025). "In the context of an inflammasome-dependent function, AIM2 can be activated by circulating dsDNA in the serum of mice treated with the carcinogen diethylnitrosamine, which promotes inflammasome-mediated inflammation and hepatocellular carcinoma progression." (PMID 41062723, 2025). "AIM2 also played a critical role in human hepatocellular carcinoma (HCC)." (PMID 38817443, 2024). "Additionally, hepatitis B virus X protein (HBx)‐mediated loss of AIM2 is correlated with a high tendency for metastasis and activation of the EMT process in HBV‐related hepatocellular carcinoma tissues, which is mediated by fibronectin 1 (FN1) expression." (PMID 34014039, 2021). "Furthermore, AIM2 expression is decreased in hepatocellular carcinoma, and low AIM2 expression contributes to hepatocarcinoma tumorigenesis and metastasis." (PMID 33859277, 2021). "In addition, transfection of human hepatocellular carcinoma cells (HepG2) with the full-length HBV genome triggered an AIM2-dependent production of IL-18 by these cells, showing that the AIM2 inflammasome is functionally active in a human hepatocyte cell line." (PMID 32906750, 2020). "However, the role of AIM2 in the development of hepatocellular carcinoma (HCC) remains to be clarified." (PMID 27167192, 2016). "In a similar vein, the expression of AIM2 in human hepatocellular carcinoma (HCC) tissues was markedly lower than in adjacent normal tissues, and patients with HCC exhibiting higher AIM2 expression demonstrated significantly improved overall survival rates." (PMID 39600708, 2024). "For example, in AIM2 overexpression and silencing in hepatocellular carcinoma cells (HCC) studies, the anticancer effect of AIM2 was mediated by inflammasomes and induced by pyroptosis." (PMID 36248785, 2022).
hepatocellular carcinoma (continued). "While the high expression of AIM2 is beneficial to the survival of tumor patients in hepatocellular carcinoma (HCC)." (PMID 36386141, 2022). "In the context of hepatocellular carcinoma (HCC), AIM2 has been found to suppress HCC cell proliferation, colony formation, and invasion by inducing pyroptosis through inflammasome formation, consequently inhibiting the mTOR-S6K1 pathway and hindering tumor progression." (PMID 39744568, 2025). "In colon, hepatocellular carcinoma (HCC), breast, renal carcinoma (RCC), and cervical cancer, decreased AIM2 expression promotes tumorigenesis and affects patient prognosis." (PMID 39450183, 2024). "Functionally, knockdown of AIM2 enhances HBX-mediated migration and metastasis of hepatoma cells." (PMID 35251017, 2022). "This demonstrated that all three receptor pathways were inducible in the hepatoma cells, and that the upregulated expression of receptors, adaptor molecules, and effector cytokines after 24 hours, especially of ZBP1/DAI and AIM2, was fairly comparable to those obtained in PWHs." (PMID 34671360, 2021). "Here, we discuss the known functions of AIM2 in the pathogenesis of different hepatic diseases, including non-alcoholic fatty liver disease (NAFLD) and non-alcoholic steatohepatitis (NASH), hepatitis B, liver fibrosis, and hepatocellular carcinoma (HCC)." (PMID 32906750, 2020). "However, the role of AIM2 in the development and progression of hepatocellular carcinoma has never been clarified." (PMID 27167192, 2016). "A study has revealed that HBx not only inhibits the mRNA expression level of AIM2 by stabilizing the enhancer of zeste homolog 2 (EZH2), but also promotes AIM2 protein degradation in a proteasome-dependent manner in HBV-infected hepatocellular carcinoma (HCC) cells." (PMID 36298831, 2022). "For confirming the presence of IFI16, ZBP1/DAI, and AIM2 in hepatocytes rather than in immune cells possibly contaminating the PWH cultures, woodchuck WCH-17 hepatoma cells were treated with HSV-60 and poly(dA:dT)." (PMID 34671360, 2021).